CPT2 (carnitine palmitoyltransferase 2)
Diseases named in the same sentence as CPT2 in open-access papers (continued):
Sharing a sentence is not in itself a finding about the gene and the disease.
leukemia (3 papers, 2016 to 2023). A malignant (clonal) hematologic disorder, involving hematopoietic stem cells and characterized by the presence of primitive or atypical myeloid or lymphoid cells in the bone marrow and the blood. "The elevated level of CPT1 and CPT2 observed in leukemia cells correlates with the prevention of cell death." (PMID 37256177, 2023). "Carnitine palmitoyl transferase 2 (CPT2), an isoform of CPT1, is also upregulated in leukaemia, PC, CRC, and HCC." (PMID 36618350, 2022). "Furthermore, we also identified a strong correlation in ETV6/RUNX1-positive leukemias between NETO1 and its adjacent, bidirectional lncRNA lnc-TIMM21-5 (r = 0.89) as well as between LRP8 and lnc-CPT2-7 (r = 0.70)." (PMID 27650541, 2016).
medium chain acyl-CoA dehydrogenase deficiency (3 papers, 2016 to 2025). "This occurs in numerous inborn errors of fatty acid oxidation such as medium chain acyl-CoA dehydrogenase deficiency (MCADD) and carnitine palmitoyl transferase II (CPT-2) deficiency." (PMID 26978356, 2016).
melanoma (3 papers, 2020 to 2021). A malignant, usually aggressive tumor composed of atypical, neoplastic melanocytes. "Comparative analyses between melanoma cells and benign nevi show that carnitine palmitoyltransferase 2 (CPT) 2, an enzyme critical for translocation of long-chain Fas, is one of the most upregulated gene in melanoma." (PMID 32528879, 2020). "The enzyme carnitine palmitoyltransferase 2 (CPT2), necessary for the translocation of long-chain FAs into the mitochondrial matrix for β-oxidation, has been identified as one of the most significantly upregulated genes in melanoma." (PMID 33498757, 2021). "For instance, carnitine palmitoyltransferase 2 (CPT2), which is critical for translocation of long-chain acyl-CoA into the mitochondrial matrix, is one of the most significantly upregulated genes in melanoma as compared to benign nevi." (PMID 33121001, 2020).
renal fibrosis (3 papers, 2021 to 2022). A final common manifestation of a wide variety of chronic kidney diseases characterized by glomerulosclerosis and tubulointerstitial fibrosis. "Mechanistically, EP4 in macrophages regulated macrophage polarization through activation of Carnitine palmitoyltransferase 2 (CPT2)-mediated lipophagy, ameliorated IRI, mitigated renal fibrosis, and prevented AKI-to-CKD transition." (PMID 36467025, 2022). "Consistent with the reports, our study showed that the gene expression of FAO-related key metabolic enzymes (CPT1A, CPT2, and ACOX2) and the FAO transcription regulatory factors (PPARα and PGC1α) were markedly decreased in renal fibrosis induced by I/R." (PMID 35526054, 2022).
Sepsis (3 papers, 2020 to 2024). Sepsis is defined as life-threatening organ dysfunction caused by a dysregulated host response to infection. "Regulating import of long-chain FAs into the mitochondrial matrix, we found increased CPT1a or b, dependent on the model, along with CPT2 induction in human sepsis." (PMID 35013270, 2022). "In conclusion, the present study demonstrates that the inhibition of mitochondrial FAO, in particular CPT2‐dependent FAO, is detrimental to cardiac function in endotoxaemia and sepsis." (PMID 32896106, 2020).
Anxiety (2 papers, 2024 to 2026). Intense feelings of nervousness, tension, or panic often arise in response to interpersonal stresses. "While CPT2 deficiency is not commonly associated with increased anxiety, our published case study documents a proband with CPT2 deficiency, anxiety, and schizophrenia." (PMID 39199302, 2024). "Moreover, we conducted the open field test to determine if the loss of CPT2 in the brain affected locomotor activity and anxiety-like behavior in mice." (PMID 41553195, 2026).
cystic kidneys (2 papers, 2017 to 2024). "For example, patients with mutations in CPT2, an enzyme that transports FA into mitochondria, or patients with Zellweger syndrome, a disorder caused due to defective peroxisomes, develop cystic kidneys." (PMID 28205547, 2017). "Notably, CPT2, encoding one of the rate-limiting enzymes for transferring fatty acids into the mitochondria during FAO, was downregulated (−1.6×) in renal cysts." (PMID 39000280, 2024).
diabetes (2 papers, 2019 to 2025). "At E10.5, effects of diabetes were significant for Slc27a6/Fatp6, Slc27a4/Fatp4, and Cpt2 (27.8%, 19.4%, and 19.7%, respectively), and for Cpt1a, Slc2a13/Glut13, and Cpt1b, diet was a significant contributor (42.9%, 38.7%, and 31%, respectively)." (PMID 31774824, 2019).
diabetic nephropathy (2 papers, 2020 to 2022). "It is well-known that downregulated or deficient CPT-1 or CPT-2 is critical to impaired FAO in diverse kidney diseases, such as ischemic and cisplatin AKI and diabetic nephropathy." (PMID 32226789, 2020). "Therefore, Cpt-1 or Cpt-2 is critical for normal oxidation of fatty acids; several studies have revealed that the downregulated or deficient Cpt-1 or Cpt-2 is critical to the impaired FAO in diverse kidney diseases, such as ischemic, cisplatin AKI, and diabetic nephropathy." (PMID 35308536, 2022).
dyslipidaemia (2 papers, 2012 to 2017). "The case of J. W. raises a number of general issues with regard to the management of dyslipidaemia in patients with subclinical atherosclerosis and musculoskeletal side effects of therapy, in addition to specific issues related to CPT2 deficiency." (PMID 23326270, 2012).
dyslipidemia (2 papers, 2021 to 2024). "Rab30 whole-body, liver-specific, and Rab30; Cpt2 liver-specific double knockout (DKO) mice are viable with intact Golgi ultrastructure, although Rab30 deficiency in DKO mice suppresses the serum dyslipidemia observed in Cpt2L−/− mice." (PMID 38796472, 2024). "Furthermore, flavan 3-ols fractions derived from cocoa powder were shown to promote lipolysis and mitochondrial biogenesis consistent with increasing β-oxidation through regulating carnitine palmitoyltransferase 2 (CPT2) expression and mitochondria copy number in mice with metabolic syndrome." (PMID 34068459, 2021).
epilepsy (2 papers, 2023 to 2025). A brain disorder characterized by episodes of abnormally increased neuronal discharge resulting in transient episodes of sensory or motor neurological dysfunction, or psychic dysfunction. "A female patient diagnosed with CPT2 deficiency, who had a prior diagnosis of epilepsy, unfortunately passed away due to status epilepticus while on triheptanoin treatment." (PMID 40448841, 2025).
gout (2 papers, 2022). A condition characterized by painful swelling of the joints, which is caused by deposition of urate crystals. "Following these analyses, two SNVs in the coding regions of two gout-associated genes (CPT2 and ABCC4) were retained." (PMID 35372350, 2022). "In conclusion, this study identifies a rare CPT2 mutation in a large Chinese pedigree with gout." (PMID 35372350, 2022). "It has been previously suggested that the interaction between CPT2 and UCP2 is associated with gout or hyperuricemia." (PMID 35372350, 2022). "To further evaluate the possible role of CPT2 in gout, we first assessed the interaction between UCP2 and wild-type CPT2, then determined the effect of the p.R631C mutation on this interaction." (PMID 35372350, 2022). "However, the association between CPT2 gene and gout has never been reported." (PMID 35372350, 2022).
liver cancer (2 papers, 2019 to 2022). An epithelial or non-epithelial malignant neoplasm that arises from the liver. "In earlier researches, the function of CPT2 in the progression of liver cancer formation was observed, and GSEA shows that CPT2 is negatively correlated with the G2M checkpoint in CRC." (PMID 36195841, 2022).
Acute encephalopathy (1 paper, 2023). "Several studies in Japan have shown an association of the CPT2 thermolabile polymorphism, in particular rs2229291 (F352C) in exon 4, with acute encephalopathy." (PMID 36761411, 2023). "The attenuation of CPT2 in acute encephalopathy may be rescued by a lipid-lowering agent, bezafibrate." (PMID 36761411, 2023).
attention deficit-hyperactivity disorder (1 paper, 2020). A disorder characterized by a marked pattern of inattention and/or hyperactivity-impulsivity that is inconsistent with developmental level and clearly interferes with functioning in at least two settings (e.g. at home and at school). "CPT1, CPT2, and the carnitine transporter SLC22A5/OCTN2 are expressed in several regions of rat brain; in addition, a deletion in the OCTN2 gene has been associated with attention-deficit/hyperactivity disorder, and mutations in the HTML gene were considered to be a risk factor in autism." (PMID 33371457, 2020).
autism (1 paper, 2023). Persistent deficits in social interaction and communication and interaction as well as a markedly restricted repertoire of activity and interest as well as repetitive patterns of behavior. "Out of these 6 autism-related genes, only 3 (CPT2, SCP2 and SSBP3) have strong orthologs in flies (DIOPT Score >0.5), with the highest orthology for SSBP3 (DIOPT Score = 0.93)." (PMID 37486945, 2023).
bladder cancer (1 paper, 2019). "The tissue mRNA expression related to acylcarnitine and carnitine metabolism (CPT1, CPT2, carnitine/acylcarnitine translocase) were downregulated, which the author proposed to result in elevated urinary acylcarnitine excretion from bladder cancer tissue." (PMID 31889746, 2019).
cholestasis (1 paper, 2017). Impairment of the bile flow caused by obstruction within the liver, or outside the liver in the bile duct system. "Quantitative real-time PCR (QPCR) analysis indicated the inhibition of Cpt1b, Cpt2, Mcad and Hadha in cholestasis was increased by fenofibrate (P < 0.01)." (PMID 28855630, 2017).
Cirrhosis (1 paper, 2017). A chronic disorder of the liver in which liver tissue becomes scarred and is partially replaced by regenerative nodules and fibrotic tissue resulting in loss of liver function. "The ratio of (AC C16 + AC C18:1)/AC C2 in HBV-associated cirrhosis was higher than those in CHB and HBV-associated HCC, which indicates an increase for the cirrhosis stage of disease progression for CPT2 activity." (PMID 28198443, 2017).
cutaneous melanoma (1 paper, 2023). A primary melanoma arising from atypical melanocytes in the skin. "An alteration at position 113 of the CPT2 protein has been found in cutaneous melanoma (X113_splice)." (PMID 37251324, 2023).
Cystic renal dysplasia (1 paper, 2022). "Furthermore, neonatal CPT2 deficiency presents within days after birth and is characterized by structural malformations including cystic renal dysplasia, indicating that CPT2 is a critical enzyme in kidney physiology." (PMID 35998043, 2022).
dilated cardiomyopathy (1 paper, 2015). Cardiomyopathy which is characterized by dilation and contractile dysfunction of the left and right ventricles. "Downregulated canonical pathways included those involved in arrhythmogenic, hypertrophic, and dilated cardiomyopathy signaling (e.g., Itgb6, Cacna1s, and Hadh), fatty acid metabolism, and peroxisome proliferator-activated receptor (PPAR) signaling (e.g., Acaa2, Cpt2, and Acsl6)." (PMID 25744495, 2015).
dystrophinopathies (1 paper, 2024). "Fifteen of the patients with CK > 500 UI/L had a diagnosis: dystrophinopathies (N = 6), myositis (N = 5), gamma-sarcoglicanopathy (N = 1), carnitine palmitoyl transferase 2 deficiency (CPT2) (N = 1), non-classified myopathy (N = 1), and neuropathy (N = 1)." (PMID 39767891, 2024).
E. coli infection (1 paper, 2018). "E. coli infection decreased Cpt2 mRNA levels in Mkp-1−/− mice but had little effect in Mkp-1+/+ mice." (PMID 30563203, 2018).
glioblastoma multiforme (1 paper, 2023). "In glioblastoma multiforme, enhanced fatty acid metabolism by co-enhancement of CPT1A and CPT2 and immune checkpoint CD47, which functions as an anti-phagocytic signal, promotes the growth of radioresistant glioblastoma multiforme cells." (PMID 37601653, 2023).
heart failure (1 paper, 2022). Inability of the heart to pump blood at an adequate rate to meet tissue metabolic requirements. "Experiments in mice have shown that a CPT2 deficiency in the heart can induce severe heart failure phenotypes." (PMID 35323659, 2022).
Hepatitis (1 paper, 2023). Inflammation of the liver. "In addition, the fatty acid β-oxidation-related proteins CPT1, CPT2, ACOX1, and ACOX2 were also affected and downregulated by the downregulation of PPARα, resulting in the accumulation of lipids in cells and aggravation of the degree of hepatitis." (PMID 38139341, 2023).
hyperglycaemia (1 paper, 2020). "In terms of lipid oxidative genes, including HMGCS2, CPT2 and CPT1A, no significant changes were observed, indicating that lipid oxidation might not be responsible for the increased lipid deposition in liver, at least not in the early stages of hyperglycaemia or hyperlipidemia induced NAFLD." (PMID 33186123, 2020).
ischemic stroke (1 paper, 2023). A stroke disorder caused by obstruction of blood flow to the brain, due to thrombotic (local blood clot formation) or embolic (due to a blood clot or other material traveling from another site) event. "Finally, we report the increased activity of CPT1 and CPT2 in the brain hemisphere damaged by ischemic stroke compared to the healthy hemisphere." (PMID 36837897, 2023).
kidney cancer (1 paper, 2020). Primary or metastatic malignant neoplasm involving the kidney. "When we overexpressed CPT2 in 786-O and ACHN kidney cancer cell lines, the cell proliferation ability was significantly inhibited." (PMID 33029112, 2020).
lipid metabolism disorders (1 paper, 2023). "Muscle CPT II deficiency, caused by mutations in the CPT2 gene, represents the commonest form of lipid metabolism disorders found in adults." (PMID 37239314, 2023).
lipodystrophy (1 paper, 2016). A congenital or acquired disorder characterized by abnormal loss or redistribution of the adipose tissue in the body. "Also, AGPAT2 involved in lipodystrophy and defects in CPT2 causes carnitine palmitoyltransferase II deficiency (Orngreen, Ejstrup & Vissing, 2003)." (PMID 27478693, 2016).
liver failure (1 paper, 2021). A liver disease characterized by the liver losing or has lost all of its function. "Given that DKO mice did not gain appreciable weight on the HFD, we suspected that the dual loss of Atgl and Cpt2 may lead to liver failure." (PMID 33491665, 2021).
lung fibrosis (1 paper, 2024). "In conclusion, these data suggested that HMGCS2 facilitated lipid metabolic of AECIIs through interacting with PPARα to promote the expression of CPT1A and CPT2 in mice lung fibrosis models." (PMID 38658970, 2024). "In conclusion, these data suggested that HMGCS2 facilitated lipid metabolism of AECIIs through interacting with PPARα, which promoted the expression of CPT1A and CPT2 in mice lung fibrosis models." (PMID 38658970, 2024). "Therefore, we assumed that HMGCS2 might act as a transcriptional coactivator of PPARα in regulating the expression of PPARα target genes such as CPT1A and CPT2 in lung fibrosis." (PMID 38658970, 2024). "Furthermore, HMGCS2 could increase the expression of CPT1A and CPT2 in lung fibrosis models in mice." (PMID 38658970, 2024). "Furthermore, HMGCS2 could increase the expression of CPT1A and CPT2 in mice with lung fibrosis." (PMID 38658970, 2024).
lung squamous cell carcinoma (1 paper, 2023). "In order to learn more about the connection between CPT2 and immunotherapy, we discovered that patients with lung squamous cell carcinoma who received anti-PDL1 and anti-CTLA-4 treatment had higher survival rates when CPT2 was highly expressed." (PMID 37251324, 2023). "It was demonstrated that survival in squamous cell lung cancer was significantly increased when CPT2 was highly expressed and treated with anti-PDL1 or anti-CTLA-4." (PMID 37251324, 2023).
Multiple Organ Failure (1 paper, 2015). A progressive condition usually characterized by combined failure of several organs such as the lungs, liver, kidney, along with some clotting mechanisms, usually postinjury or postoperative. "To date, more than 70 different mutations of CPT2 have recently been reported, and studies have demonstrated the relationships between the CPT II deficiency genotypes and their clinical phenotypes characterized by febrile convulsions and multiple-organ failure during high fever." (PMID 25781464, 2015).
ovarian epithelial tumor (1 paper, 2023). A benign, borderline, or malignant tumor that originates from the surface epithelium of the ovary. "Through the mutation analysis website, we found that CPT2 had a high mutation rate in ovarian epithelial tumors and sarcoma, and the mutation types were predominantly missense mutations." (PMID 37251324, 2023).
pulmonary edema (1 paper, 2020). Accumulation of fluid in the lung tissues causing disturbance of the gas exchange that may lead to respiratory failure. "The results showed that individuals with ritodrine-induced pulmonary edema had a significantly higher number of homozygous (CPT2 rs2229291, GG) or heterozygous (CPT2 rs2229291, TG) variants than those without." (PMID 33166306, 2020). "In the current study, we demonstrated that two variants in CPT2 and ADRA1A were selected as candidate variants for pulmonary edema." (PMID 33166306, 2020). "In silico analysis of deleterious variants was performed, producing two putative East Asian population-specific variants, rs2229291 (CPT2) and rs2229126 (ADRA1A), located in genes with roles compatible with tocolytic-associated pulmonary edema." (PMID 33166306, 2020). "In the current study, we identified two final candidate variants in CPT2 and ADRA1A associated with ritodrine-induced pulmonary edema." (PMID 33166306, 2020). "Finally, the two final candidate variants located in CPT2 and ADRA1A were selected to be responsible for ritodrine-induced pulmonary edema." (PMID 33166306, 2020). "Overall, the altered dysfunction in CPT2 may contribute to the pathogenesis of pulmonary edema through decreased function in the right ventricle and increased vascular permeability in lung tissue." (PMID 33166306, 2020).
renal carcinoma (1 paper, 2020). A carcinoma arising from the epithelium of the renal parenchyma or the renal pelvis. "Subsequently, we used a plasmid transfection technology to establish CPT2 overexpressing renal cancer cell lines (786-O and ACHN cell lines) and conducted CCK-8 experiments." (PMID 33029112, 2020).
renal clear cell carcinomas (1 paper, 2024). "For renal clear cell carcinoma, CPT2 was able to promote the malignant biological behavior of cells, as well as increase sorafenib resistance by inhibiting FAO and decreasing NADPH (nicotinamide adenine dinucleotide phosphate), thereby activating the ROS/PPARγ/NF-κB pathway." (PMID 39596847, 2024).